ZHX1 (zinc fingers and homeoboxes 1)
Diseases named in the same sentence as ZHX1 in open-access papers (continued):
Sharing a sentence is not in itself a finding about the gene and the disease.
cancer (14 papers, 2011 to 2025). A tumor composed of atypical neoplastic, often pleomorphic cells that invade other tissues. "For example, in CTLL-2 cells (cytotoxic T cells), IL-2 increased ZHX1 gene expression and CTLL-2 proliferation, and in malignant breast cancer, an elevated ZHX1 level was associated with cancer cell invasion." (PMID 27835650, 2016). "Furthermore, a higher ZHX1 expression was associated with a better prognosis of the patients who received surgery therapy and in the patients whose cancer showed poor differentiation." (PMID 36232466, 2022). "Three analyses revealed attenuated ZHX1 mRNA expression in cancer tissues than in normal tissues, whereas two other analyses showed an opposite result." (PMID 41480542, 2025). "Results obtained for FBXO32, ZHX1 and ANXA13 genes encoded within the same region as ATAD2 clearly emphasize the specificity of ATAD2 and MYC as well as ATAD2 and cancer stemness associations." (PMID 35049055, 2022). "The lncRNA DLG1-AS1 acts as a competitive inhibitor that influences the activity of miR-107 on its target gene ZHX1, thereby inducing cancer cell proliferation." (PMID 32102656, 2020). "ZHX1 interacts with the activation domains of NF-YA, BS69, and DNMT3B, and possible association with the progression of various cancers has also been suggested in previous studies." (PMID 27835650, 2016). "ZHX1 is a novel transcription factor and was recently discovered in a mouse bone marrow stromal cell line, and thus, comparatively little is known of the pathophysiological roles of ZHX1 during cancer progression." (PMID 27835650, 2016). "Nevertheless, recent reports have implied that ZHX1 might serve as an oncogene and its overexpression was correlated with a worse prognosis in cancers." (PMID 41480542, 2025). "Thus, the prognostic impact of ZHX1 on various cancer types, even in their subtypes, appears to be contradictory." (PMID 41480542, 2025). "The regulation of ZHX1 expression, its clinical significance, and role in cancer is controversial." (PMID 36232466, 2022). "ZHX1 contributes to cancer cell proliferation, mobility, migration, and invasion." (PMID 36232466, 2022). "ZHX1 acts as an oncogene or tumor suppressor in different types of cancer." (PMID 36232466, 2022). "We first analyzed ZHX1 gene alteration in various cancers using TCGA data." (PMID 27835650, 2016). "Furthermore, restoring ZHX1 expression inhibits cancer cell proliferation in vitro." (PMID 36232466, 2022). "However, other studies reported that ZHX1 suppressed proliferation of cancer cells." (PMID 31648104, 2019). "ZHX1 has been identified as the first member of the ZHX family, and has been reported as a tumor suppressor in several types of cancer." (PMID 41480542, 2025). "Experimental evidence points to the role of Zinc fingers and homeoboxes protein 1 and 2 (ZHX1 and ZHX2) in the development and progression of several types of cancer, including hematological malignancies." (PMID 33541423, 2021). "Presently, the mechanisms behind ZHX1’s pro or anti-carcinogenic role in different cancer types are still not fully elucidated." (PMID 31648104, 2019). "In the present study, the expressions of ZHX1 and ZHX3 were reduced in ccRCC, but the expression of ZHX2 was increased in ccRCC compared to the normal tissues, which suggests the expressions of ZHX family members are cancer type-specific." (PMID 28152006, 2017). "Although it is now well established that ZHX1 and ZHX2 worked as tumor suppressors, the role of ZHX3 in cancer is not clear." (PMID 31856408, 2020).
tumor (9 papers, 2017 to 2025). "In nude mice, the ZHX1 overexpression inhibited the tumor growth that was associated with cell cycle arrest and a repressed expression of cyclin D1." (PMID 36232466, 2022). "Mechanistic studies showed that ZHX1-mediated tumor promotion might be partially associated with early growth response 1 (EGR1)." (PMID 36232466, 2022). "It has been reported that long non-coding RNA (lncRNA), microRNA (miRNA), and ZHX1 participate in tumor initiation and progression." (PMID 36232466, 2022). "For the Zinc fingers C2H2-type|PR/SET domain family, one of its members, ZHX1, was regulated by a cluster of five enhancers in 22 samples, which covered 12% of 184 tumor sample with detected super-enhancer regulation." (PMID 29207666, 2017). "One study detected a decreased ZHX1 expression from a HCC tumor and cell sample." (PMID 36232466, 2022). "Interestingly, the reduced nuclear expression of ZHX1 was closely related to a larger tumor size, poorer differentiation, advanced TNM stages, and a deeper invasion." (PMID 36232466, 2022). "Altogether, these findings indicate that ZHX1 is a tumor suppressor in renal cancer." (PMID 36232466, 2022). "MALAT1 also promoted tumor invasiveness via regulating the miR-199a/ZHX1 axis." (PMID 34322395, 2021). "Another study also showed the tumor-suppressive roles of ZHX1 in HCC, in which miR-199a-3p targeting the ZHX1/PUMA signal was reported to inhibit tumorigenesis." (PMID 36232466, 2022). "The tumor suppressor ZNFs include ZNF750, ZNF185, and zinc fingers and homeoboxes-1 (ZHX1)." (PMID 35463825, 2022). "The expressions of ZHX1 and ZHX3 in most ccRCC tissues were lower than in paired non-tumor tissues, whereas ZHX2 expression was higher in most ccRCC tissues." (PMID 28152006, 2017).
infection (1 paper, 2024). The state of being infected such as from the introduction of a foreign agent such as serum, vaccine, antigenic substance or organism. "The infection experiment followed Koch's postulates, indicating that zhx1 was the pathogenic bacteria causing Chinese sturgeon disease." (PMID 38781928, 2024). "Artificial infection experiments confirmed the role of zhx1 as the pathogen responsible for the deaths." (PMID 38781928, 2024).
ZHX1 also shares sentences with these, for which no sentence is quoted: acute lymphoblastic leukemia (1 paper); bladder cancer (1); gastric tumor (1); lung squamous cell carcinoma (1); T-cell acute lymphoblastic leukemia (1).